RN7SKP198 (RN7SK pseudogene 198)
Gene: Miscellaneous RNA gene on chromosome 7 (102,857,450 to 102,857,755, forward strand). Ensembl gene ENSG00000238324.
Homologues: Orthologues: chimpanzee 7SK (99% identical). Paralogues in human: RN7SKP230 (75% identical), RN7SKP171 (74% identical), RN7SKP189 (74% identical), RN7SKP176 (73% identical), RN7SKP86 (73% identical), RN7SKP71 (73% identical), RN7SKP9 (73% identical), RN7SKP255 (72% identical), RN7SKP211 (72% identical), 7SK (72% identical), RN7SKP146 (72% identical), RN7SKP180 (72% identical), and 284 more.